TGFB1 (transforming growth factor beta 1)
Diseases named in the same sentence as TGFB1 in open-access papers (continued):
Sharing a sentence is not in itself a finding about the gene and the disease.
keloid (251 papers, 2004 to 2026). An irregularly shaped, elevated mark on the skin caused by deposits of excessive amounts of collagen during wound healing. "In keloids, TGFβ-1 has been associated with increased collagen and fibronectin synthesis by fibroblasts." (PMID 37895153, 2023). "For instance, several polymorphisms in the TGFβ1 gene, such as -988C/A, -800G/A and -509C/T in the promoter region, and the mutations like Arg25Pro and Leu10Pro in exon 1, as well as Thr263Ile in exon 5, have been shown to predispose individuals to keloids." (PMID 38338767, 2024). "TGFβ1 is a key cytokine in the biological function of fibroblasts, and its irregularity—caused by gene polymorphisms or mutations—has been suggested to result in keloid development." (PMID 38338767, 2024). "In keloids, knockdown of fibronectin-1 has been shown to inhibit TGFB1-mediated cell proliferation and collagen deposition via AKT/ERK signalling pathway." (PMID 41465196, 2025). "TGFB1 is recognized as a central mediator responsible for initiating and sustaining the fibrotic response in hypertrophic scars and keloids." (PMID 41465196, 2025). "Multi-omics investigations, including proteomics, have identified abundant levels of collagens (I and III), FN1, THBS1, and TGFB1 in keloids compared to normal skin." (PMID 41465196, 2025). "On the contrary, basic fibroblast growth factor (bFGF) reduced keloid and promoted wound healing by inhibiting TGFβ1/Smad-dependent pathway." (PMID 39799030, 2025). "IL-6, IL-1β, IL-1α, and IL-8 are highly expressed in keloid fibroblasts, and induce the expression of TGFβ1 or render scars more sensitive to external stimuli, thus contributing to the continuous scar expansion and keloid formation." (PMID 38338767, 2024). "In detail, it has previously been found that ATF3 induces proliferation and invasion and inhibits apoptosis via TGFβ1/SMAD2/3 signalling in keloid fibroblasts." (PMID 38256034, 2024). "The interactions between TGFβ1 and its receptors, TGFβR1 and TGFβR2, were markedly increased in keloid compared to normal scar." (PMID 34140509, 2021). "In keloids, fibroblasts are more sensitive to TGFβ1 than in normal skin, and their density and proliferation rate are high, whereas apoptosis is lower." (PMID 31231509, 2019). "Transforming growth factor beta 1 (TGF-β1)-mediated up-regulation of microRNA-21 increases the expression of MMP9 in keloid fibroblasts, wherein it promotes fibroblast proliferation and transdifferentiation." (PMID 29186868, 2017). "We found that fibroblasts may affect other cells in the keloid through alterations in ligand–receptor interactions of TGFβ1 signaling." (PMID 34140509, 2021). "In keloids, growth factors, such as IGF-1 and TGFβ1, are closely associated with the pathogenesis of keloids, and fibroproliferation has been reported to be regulated—in part—by the ERK pathway, which is signaled by receptor tyrosine kinase phosphorylation by IGF-1." (PMID 32182995, 2020). "Moreover, in hypertrophic scars, the expression of TGFβ1 and TGFβ2 is lower compared with keloids whereas the expression of TGFβ3 is higher." (PMID 31231509, 2019). "Similarly, it has been shown that pirfenidone inhibited collagen gel contraction and TGFβ1 induced α-SMA production of keloid derived fibroblasts." (PMID 26846335, 2016). "Additionally, EDN1 and NTF3 exhibited high correlations with fibrosis markers (COL1A1, TGFB1), inflammatory cytokines (IL6, TNFA), and immune cell infiltration (e.g., activated mast cells), suggesting their central regulatory roles in keloid-associated fibrosis and inflammation." (PMID 40051702, 2025). "Treg markers, FOXP3 and TGFβ1, and T-cell activation measure ICOS, were up-regulated in lesional keloid versus normal skin (P<0.05 for TGFβ1)." (PMID 33329590, 2020). "Each transforming growth factor beta (TGF-β) subclass has a different role in wound healing, and transforming growth factor beta 1 (TGF-β1) is well known as an important growth factor in keloid formation." (PMID 31890007, 2019).
keloid (continued). "Additionally, PBMT attenuates the expression of transforming growth factor-beta 1 (TGF-β1), a central mediator in keloid pathogenesis, and inhibits its downstream Smad signaling pathway, further decreasing fibroblast activation and collagen production." (PMID 40703263, 2025). "-SDC-1 is induced in keloid tissues/fibroblasts, driving ECM accumulation via TGFβ1/Smad and MAPK." (PMID 41226609, 2025). "Here, we observed for the first time that keloid epidermis and in a lesser extent hypertrophic scar epidermis express large amounts of NOX4, and that TGFβ1 induces the expression of NOX4 and reactive oxygen species which is inhibited by roflumilast and siRNA-PDE4B." (PMID 39223490, 2024). "Primary keratinocytes from keloid scar and normal skin were cultured in the presence or absence of transforming growth factor beta 1 (TGF-β1) +/− inhibitors of TGF-β1 and downstream signaling pathways." (PMID 27574697, 2016). "This combined analysis included keloid datasets (GSE32413, GSE44270, GSE76807, GSE188952, GSE212954, GSE246562), bleomycin (BLM)-induced fibrotic mice skin datasets (GSE71998, GSE226331), and transforming growth factor-beta 1 (TGF-β1)-treated fibroblast datasets (GSE99999, GSE264288)." (PMID 39919369, 2025). "Moreover, transforming growth factor beta 1 (TGF-β1) enhances the expression of early growth response factor-1 (EGR1) in keloids by modulating the small mother against decapentaplegic (SMAD) pathway, thereby promoting the fibrotic phenotype of keloid fibroblasts." (PMID 38671903, 2024).
lung adenocarcinoma (251 papers, 2002 to 2026). A carcinoma that arises from the lung and is characterized by the presence of malignant glandular epithelial cells. "However, when the data were stratified for cooking oil fume exposure, the TT genotype of the TGFB1 C509T polymorphism showed a significantly decreased risk for lung adenocarcinoma compared with the CC genotype (adjusted OR=0.362, 95% CI=0.149–0.878, P=0.025)." (PMID 25928368, 2015). "In HEK-293T cells, TGFB1 overexpression increased β-catenin and Snail expression, accompanied by a corresponding downregulation of E-cadherin and Vimentin, indicating that TGFB1 strongly promotes EMT in EGFR-mutant lung adenocarcinoma cells." (PMID 40234395, 2025). "In the process of EMT, TGFβ1 upregulated ST6GALNAC5 in A549 lung adenocarcinoma cells, while another EMT negative regulator miR-200b downregulated ST6GALNAC5 through directly targeting its 3’UTR." (PMID 37468844, 2023). "To re-program normal fibroblasts into CAFs, HFL1 cells were either treated with TGFβ1 (myCAFs), or with IL1α to activate them into iCAFs, or were co-cultured with the lung adenocarcinoma cells." (PMID 36635266, 2023). "Previous research has shown that the EMT can be triggered by the transforming growth factor-beta 1 (TGF-β1), which in turn encourages the migration and invasion of lung adenocarcinoma cells." (PMID 36139697, 2022). "CXCR7 is up-regulated most compared with other chemokine receptor by TGFβ1 in human lung adenocarcinoma A549 cell line." (PMID 33129326, 2020). "It was reported that TGFβ1 stimulation of the epithelial-like lung adenocarcinoma cell line H1437 triggered upregulation of cytoskeletal proteins and induced a more aggressive cell phenotype." (PMID 29934580, 2018). "By integrating two time-course microarray data in human lung adenocarcinoma cells, we specifically have identified some nested gene clusters and found that TGFB1, EGR1, EGR2, EGFR, IL6, JUN, and JUNB all are involved in these clusters." (PMID 28959347, 2017). "We went on to utilise two lung cell lines to assess EMT induction in response to either TGFβ1 or mir-200c: Beas2B (immortalised bronchial epithelial cells) and A549 (lung adenocarcinoma cells)." (PMID 22045191, 2012). "Interestingly, treating lung adenocarcinoma with TGFβ1 suppressed tumor growth and transformation of cell phenotypes by maintaining intracellular actin filament organization; however, treating with activin A did not have the same effect." (PMID 41463203, 2025). "To understand the role of TGF-β signaling in lung adenocarcinoma progression, we initially found that the activity of TGF-β signaling, which is defined as the average of TGFB1 and SERPINE1 expression, significantly correlated with poor prognosis of LAD patients in the TCGA LUAD cohort." (PMID 37072414, 2023). "Thus, using OncoLnc, Kaplan–Meier analysis revealed that in lung adenocarcinoma and cutaneous melanoma, high expression of both MIR100HG and TGFB1 was linked to long patient survival, suggesting their tumor-suppressive role." (PMID 33941855, 2021). "Regarding mechanisms, the AHSA1-HSP90AA1 complex stabilizes IFI6 and TGFB1 to enhance cell survival and Osimertinib resistance in EGFR mutant lung adenocarcinoma." (PMID 40234395, 2025). "The pharmacodynamic results, such as for relative tumor volumes and tumor inhibition rates, reveal that TGFβ1 siRNA LNPs modified with CE1.5, CE2.5, or TPGS2.5 can be used to effectively treat paclitaxel-resistant lung adenocarcinoma." (PMID 38258086, 2024). "We found that TGFB1, ENG, TGM2, TBXA2R, HSPG2, and PTPRS were significantly upregulated in lung adenocarcinoma cells." (PMID 36249427, 2022). "SDC4 is known to positively regulate TGFβ1-induced EMT (via Snail) in lung adenocarcinoma cells, whilst SDC4-signalling negatively regulates the production of TGFβ1 (reported in the kidneys of SDC4 KO mice)." (PMID 34282767, 2021).
lung adenocarcinoma (continued). "In contrast, SDC4 promotes cell migration and invasion of A549 lung adenocarcinoma cells both in wound healing and chemotaxis assays and SDC4 positively regulates TGFβ1-mediated EMT via Snail." (PMID 34282767, 2021). "TGFβ1 siRNA LNPs modified with CE1.5, CE2.5, or TPGS2.5 could be used to effectively treat paclitaxel-resistant lung adenocarcinoma." (PMID 38258086, 2024). "Tip cell proportions were elevated in early‐stage lung adenocarcinoma (LUAD) tissues and KT mice, with evidence suggesting they arise from capillaries type I. PLVAP expression was enriched in tumour endothelial cells, induced by TGFβ1, and negatively correlated with patient prognosis." (PMID 41431249, 2025). "TGFβ1 siRNA LNPs modified with CE1.5, CE2.5, and TPGS2.5 can inhibit TGFβ1 mRNA and protein expression in A549/T cells in vitro and can accumulate and play a role in the tumor tissue of nude mice, features that can be exploited for treating paclitaxel-resistant lung adenocarcinoma." (PMID 38258086, 2024). "Moreover, transforming growth factor beta-1 (TGFβ1)-induced EMT is paralleled by upregulation of voltage-gated EAG1 (Ether-à-go-go-1, Kv10.1) K+ channels in lung adenocarcinoma cells and inhibited by KCa3.1 (IK) K+ channel blockade in bronchial epithelial cells." (PMID 27618016, 2016).
glomerulosclerosis (247 papers, 2010 to 2026). A hardening of the kidney glomerulus caused by scarring of the blood vessels. "In the present study, we found that the overexpression of TGFβ1 in the kidneys is associated with insulin resistance and the rapid progression of glomerulosclerosis under diabetic conditions in mice." (PMID 36430743, 2022). "TGFβ1 has been shown to play important roles in podocyte apoptosis/loss and development of glomerulosclerosis." (PMID 29415466, 2018). "The attenuated progression of glomerulosclerosis, mesangial expansion, and fibrosis marker expression (e.g., Col4a1, Tgfb1) in p66Shc−/− mice highlights a direct role for this protein in modulating the structural remodeling associated with renal aging." (PMID 41303581, 2025). "Elevated TGFB1 plasma levels have been associated with the progression of renal disease due to increased ECM production, leading to glomerulosclerosis and tubulointerstitial fibrosis." (PMID 37418683, 2023). "TGFβ1 contributes to apoptosis in various types of kidney cells including the tubular epithelial cells during kidney fibrosis and glomerulosclerosis." (PMID 33299873, 2020). "Since the landmark studies of Border and colleagues demonstrating a role for transforming growth factor beta 1 (TGF-β1) in glomerulosclerosis, a multiplicity of evidence has implicated TGF-β1 as the pre-eminent fibrogenic cytokine." (PMID 28848437, 2017). "SFR exerts potent effects of alleviating glomerular sclerosis and interstitial fibrosis in the kidney, mainly via integrated regulations on metabolism and production of homocysteine, L-carnitine, and epinephrine, as well as the expression of TGFβ-1." (PMID 32908562, 2020). "Histologically, the extent of glomerulosclerosis and tubular atrophy, the amount of collagen deposition, interstitial fibrosis, inflammatory monocyte infiltration, and expression of transforming growth factor beta 1 (TGF-ß1), and superoxide dismutase 1 (SOD-1) were examined." (PMID 32015680, 2020). "We speculate that Trio may have dual roles; it may play important roles in podocyte development but it may also regulate pathological Rac1 hyperactivation in the context of TGFβ1-mediated podocyte injury and glomerulosclerosis." (PMID 29415466, 2018). "The combination of prenatal hypoxia and the challenge of a chronic high salt diet in postnatal life was strongly associated with marked elevations in mRNA expression of Kim-1 and Tgfb1 in combination with increased glomerulosclerosis and fibrosis in the male offspring at 12 month of age." (PMID 28811528, 2017). "Transforming growth factor 1 (TGFβ1), a cytokine with multiple biological activities known to be a fibrogenic factor that leading to ECM deposition and an important regulator of glomerular sclerosis." (PMID 37790634, 2023). "The non-diabetic TGFβ1 TG mice and diabetic WT mice showed significantly higher glomerulosclerosis scores than the non-diabetic WT mice." (PMID 36430743, 2022). "The glomerulosclerosis score was not significantly increased in the diabetic TGFβ1 TG mice compared to the non-diabetic TGFβ1 TG mice but significantly increased in the diabetic TGFβ1 TG mice compared to the diabetic WT mice." (PMID 36430743, 2022).
heart failure (247 papers, 2009 to 2026). Inability of the heart to pump blood at an adequate rate to meet tissue metabolic requirements. "Polymorphisms in TGFB1 have been associated with heart failure caused by DCM, and TGFβ is upregulated in the plasma and myocardium of DCM patients." (PMID 26918958, 2016). "There is compelling evidence to suggest that TGFβ1 is associated with various cardiac pathologies involved in heart failure." (PMID 28509980, 2015). "Aberrant TGFβ1 signalling contributes to the development of a multitude of conditions associated with heart failure such as dilated and hypertrophic cardiomyopathies, post-infarction myocardial remodelling, valvular diseases and arrhythmia in both mice and humans." (PMID 28509980, 2015). "miR-21, miR-425, and miR-744 were downregulated in heart failure patients’ plasma exosomes, and overexpression attenuated fibrogenesis in cardiac fibroblasts by targeting TGFβ1." (PMID 37663746, 2023). "In the sinus node of the heart failure mice, qPCR showed that there was a trend of an upregulation of the proinflammatory cytokine, TGFβ1, as well as a significant upregulation of the major collagen isoform in the heart, collagen type 1 α1." (PMID 32647133, 2020). "A further functional study proved that they negatively regulated cardiac fibrosis by suppressing TGFβ1 expression, revealing their potential role in regulating and predicting heart failure." (PMID 33392270, 2020). "TGFβ1 coordinates a broad spectrum of cellular processes that contributes to cardiac remodelling after MI and subsequent progression to heart failure." (PMID 28509980, 2015). "Recently, reduction of the glycoprotein endoglin, a co-receptor of TGFβ1 signaling in the cardiac fibroblast, correlates with an attenuation of cardiac fibrosis in patients with heart failure." (PMID 23423152, 2013). "Similarly, GRB2 is a downstream protein in the transforming growth factor beta 1 stimulated myofibroblast transformation process in cardiac fibrosis and heart failure." (PMID 39863867, 2025). "Importantly, TGFβ1 expression was found to increase particularly during the transition from stable to symptomatic heart failure." (PMID 30895179, 2019). "We demonstrate here that mice with calreticulin overexpression, which were used to model heart failure, developed extensive cardiac fibrosis due to transient activation of UPR which in turn underlies the subsequent stimulation of the TGFβ1/Smad2/3 signaling pathway." (PMID 27441395, 2016). "Although activation of UPR may have promoted cardiomyocyte survival, the permanent activation of TGFβ1 pathways led to cardiac pathology and heart failure." (PMID 27441395, 2016). "A strategy that selectively attenuates the fibrogenic effect but stimulates the pro-angiogenic aspect of TGFβ1 may serve as an ideal treatment option for heart failure." (PMID 28509980, 2015). "Furthermore, genes for fibrotic regulators, such as TGFβ1, TIMP1, TIMP3, TIMP4, and ADAMTS1, were linked to CLIC expression, reinforcing the hypothesis that CLICs contribute to fibrotic progression and ECM remodeling in human heart failure." (PMID 41521401, 2026). "Consequently, the level of transforming growth factor beta 1 (TGF‐β1) increases, prompting the conversion of cardiac fibroblasts into myofibroblasts and leading to excessive synthesis of collagen, fibronectin, and proteoglycans and at last causing heart failure." (PMID 39432214, 2024). "Mutations in genes of the canonical signaling pathway, i.e., TGFB1/2/3, TGFBR1/2, and SMAD2/3/4, result in CVDs such aortic aneurysms and aortic dissections, congenital heart defects, cardiac arrythmias, and heart failure." (PMID 38324186, 2024). "Thus, targeting the TGFβ1 signalling pathway might provide an attractive strategy to limit structural deterioration of myocardium and ultimately lead to improved cardiac function, and survival of heart failure patients." (PMID 28509980, 2015).
heart failure (continued). "In this review, we summarise the current knowledge on the role of TGFβ1 and its novel modulator, LRG1, in different pathologies of cardiac remodelling and the potential of LRG1-targeted therapeutics for the treatment of heart failure." (PMID 28509980, 2015). "In addition, we do not found any differences for TGFβ1, TβRI, and TβRII mRNA gene expression among healthy, ascetic, and chickens with cardiac failure." (PMID 24286074, 2013).